NEAT1 (nuclear paraspeckle assembly transcript 1)
Diseases named in the same sentence as NEAT1 in open-access papers (continued):
Sharing a sentence is not in itself a finding about the gene and the disease.
osteosarcoma (continued). "The lncRNA NEAT1/miR-483/STAT3 axis regulated the EMT and metastasis of osteosarcoma cells, which might represent new drug targets for the treatment of osteosarcoma in the future." (PMID 33546665, 2021). "However, the potential regulatory effects of NEAT1 and miR-483 on the EMT of osteosarcoma remain elusive." (PMID 33546665, 2021). "As shown in a recent study by Zhang and colleagues, NEAT1 promotes the proliferation, invasion and migration of osteosarcoma cells via the miR-339-5p/TGF-β1 pathway, which subsequently facilitated the progression of osteosarcoma." (PMID 33546665, 2021). "Moreover, the effects of NEAT1 on promoting the EMT and metastasis of osteosarcoma cells were confirmed in vivo." (PMID 33546665, 2021). "Recently, our lab identified putative binding sites for miR-483 in NEAT1 using a bioinformatics analysis, suggesting that NEAT1 might participate in the mechanism regulating the EMT and metastasis of osteosarcoma by sponging miR-483." (PMID 33546665, 2021). "However, NEAT1 sponged miR-438, increased STAT3 expression, and repressed STAT1 expression, subsequently increasing the EMT of osteosarcoma cells." (PMID 33546665, 2021). "With data showing NEAT1 is overexpressed in osteosarcoma tissue in comparison to non-malignant tissues." (PMID 35582574, 2019). "Both qRT‐PCR and Western blot results showed that overexpression of wild‐type NEAT1 upregulated HOXA13 expression in osteosarcoma cells, whereas mutant‐type NEAT1 did not disrupt base pairing between NEAT1 and miR‐34a‐5p." (PMID 31044561, 2019). "Using dual luciferase assay and RIP experiments, we identified miR-483 as a target of NEAT1, and the exogenous expression of NEAT1 reduced miR-483 expression, subsequently upregulating the expression of N-cadherin, Vimentin and Snail and promoting the EMT in osteosarcoma cells." (PMID 33546665, 2021). "Overall, the identification of NEAT1/miR-483/STAT3 axis contributed to the elucidation of the regulatory network involved in the progression of osteosarcoma and provided insights into the prognosis and development of targeted therapy for osteosarcoma in the future." (PMID 33546665, 2021). "In this study, we examined NEAT1 in osteosarcoma tissues and adjacent noncancerous tissues." (PMID 31044561, 2019). "We overexpressed NEAT1 in U2OS cells in the absence or presence of miR-483 mimics, and then conducted the wound healing and transwell experiments to examine the effect of NEAT1 overexpression on the migration and invasion of osteosarcoma cells and to verify this hypothesis." (PMID 33546665, 2021). "However, the role of NEAT1 in the EMT of osteosarcoma has not been reported." (PMID 33546665, 2021).
acute promyelocytic leukemia (23 papers, 2014 to 2024). An aggressive form of acute myeloid leukemia (AML), characterized by arrest of leukocyte differentiation at the promyelocyte stage, due to a specific chromosomal translocation t(15;17) in myeloid cells. "On the contrary, NEAT1 was repressed in de novo acute promyelocytic leukemia compared with healthy donors and NEAT1 KD blocked myeloid differentiation." (PMID 39032650, 2024). "NEAT1 is downregulated in acute promyelocytic leukemia, where it promotes leucocyte differentiation." (PMID 37946156, 2023). "In contrast to solid tumors, NEAT1 expression is downregulated in acute promyelocytic leukemia and functions as a tumor suppressor by promoting leukocyte differentiation." (PMID 35676702, 2022). "NEAT1, especially its isoform NEAT1-1, facilitates the growth and metastasis of various cancers, excluding acute promyelocytic leukemia." (PMID 36011001, 2022). "In contrast, inhibition of NEAT1 has been shown to impair myeloid differentiation in promyelocytic leukemia cells." (PMID 33544756, 2021). "The inhibition of NEAT1 impairs myeloid differentiation in acute promyelocytic leukemia (APL) cells, correlating with a malignant phenotype." (PMID 33291485, 2020). "In hematological system tumors, lncRNA NEAT1 expression has been revealed to impair myeloid differentiation in acute promyelocytic leukemia cells." (PMID 26055877, 2015). "Promyelocytic leukemia with retinoic acid receptor alpha (PML-RARα)-fusion-mediated NEAT1 transcriptional repression might impair the myelopoiesis of acute promyelocytic leukemia cells." (PMID 34502451, 2021). "As pointed out by those investigators, the decrease in NEAT1 expression may be explained by the repression of NEAT1 by a transcriptional repressor as promyelocytic leukemia-retinoic acid receptor α (PML-RARα)." (PMID 33670447, 2021). "However, in acute promyelocytic leukemia, NEAT1 expression is reduced and functions as a tumor suppressor by promoting leukocyte differentiation." (PMID 29654165, 2018). "However, reduced levels of Neat1 impairs myeloid differentiation in acute promyelocytic leukemia cells." (PMID 28837672, 2017). "Consequently, enhancing NEAT1 expression may improve the efficacy of ATRA treatment, positioning NEAT1 as a potential therapeutic target for acute promyelocytic leukemia." (PMID 39715205, 2024). "Intriguingly, NEAT1 suppresses tumorigenesis in acute promyelocytic leukemia (APL) by accelerating APL cell differentiation." (PMID 38177154, 2024). "NEAT1 is demonstrated to be involved in acute promyelocytic leukemia (APL), acute myeloid leukemia (AML), acute lymphoblastic leukemia (ALL), and also CML." (PMID 34354942, 2021). "NEAT1 is induced strongly in breast cancer cells and is also involved in the transformation of myeloid cells into acute promyelocytic leukemia (APL)." (PMID 26082843, 2015).
diabetic nephropathy (22 papers, 2019 to 2025). "LncRNA NEAT1 plays a crucial regulatory role in various diabetes-related complications, including diabetic retinopathy, diabetic nephropathy, and impaired wound healing associated with diabetes." (PMID 39439564, 2024). "Considering these findings in conjunction with our results, NEAT1 holds significant potential as both a diagnostic biomarker and a therapeutic target in the management of diabetic nephropathy." (PMID 39439564, 2024). "NEAT1 promotes NLRP3 inflammasome activation in diabetic nephropathy and enhances macrophage inflammation in SLE." (PMID 41457558, 2025). "demonstrates that lncRNA NEAT1 plays a significant role in the pathogenesis of diabetic nephropathy by modulating extracellular matrix proteins and EMT through the miR-27b-3p/ZEB1 axis." (PMID 39439564, 2024). "Complementary research has demonstrated the capacity of NEAT1 to promote diabetic nephropathy progression via activation of the Akt/mTOR signaling pathway." (PMID 39439564, 2024). "Inhibition of NEAT1 in a diabetic kidney disease mouse model had a protective effect against EMT and renal fibrosis." (PMID 37056054, 2023). "Ablation of lncRNA NEAT1 attenuated proliferation, fibrosis and inflammation of mouse mesangial cells in diabetic nephropathy." (PMID 36313695, 2022). "LncRNA NEAT1 activated Akt/mTOR pathway and accelerated cell fibrosis and proliferation in diabetic nephropathy." (PMID 36313695, 2022). "LncRNA nuclear-enriched abundant transcript 1 (NEAT1) was reported to promote the progression of EMT in diabetic nephropathy." (PMID 34386303, 2021). "miR-34c mediates the effect of NEAT1 on diabetic nephropathy pyrophosphorylation by regulating NLRP3 expression as well as caspase-1 and interleukin-1β expression." (PMID 34712322, 2021). "A team led by Yao-Ming Xue from Southern Medical University in Guangdong, China, showed that levels of NEAT1 are elevated in mouse models of diabetic kidney disease and in injured human kidney calls." (PMID 32054986, 2020). "The Real-time PCR data showed that NEAT1 expression in patients with diabetic nephropathy was significantly higher than that in controls." (PMID 33585566, 2020). "However, NEAT1 knockdown alleviated proteinuria and kidney damage in diabetic mice, indicating that elevated Neat1 expression contributes to the development of diabetic kidney disease (DKD)." (PMID 40619276, 2025). "NEAT1 was also found to play significant roles in diabetic nephropathy in a rat model." (PMID 41457558, 2025). "In addition, lncRNA NEAT1 accelerated diabetic nephropathy occurrence and progression via suppression of miR-23c." (PMID 36313695, 2022). "Epithelial-mesenchymal transition (EMT) of retinal pigment epithelium (RPE) cells is the key of the development of diabetic retinopathy (DR), and lncRNA NEAT1 could accelerate EMT in diabetic nephropathy." (PMID 34386303, 2021). "More importantly, NEAT1/miR-27b-3p axis has been confirmed in diabetic nephropathy." (PMID 33292252, 2020). "The correlation between Klotho and NEAT1 provides novel insight into the mechanism by which Klotho may be used to treat diabetic kidney disease." (PMID 32054986, 2020). "In agreement with this hypothesis, a recent work demonstrated that Neat1 repression led to decreased proliferation and fibrosis in diabetic nephropathy via activation of the Akt/mTOR signaling pathway." (PMID 31634682, 2019). "In an in vitro model of diabetic nephropathy, either miR-34c inhibition or NLRP3 overexpression by sh-NEAT1 transfection reverses the exacerbation of pyrophosphorylation and inflammation." (PMID 34712322, 2021). "Moreover, lncRNA NEAT1 promoted fibrosis, inflammation, proliferation and oxidative stress by modification of the miR-423/5p and GLIPR2 pathway in diabetic nephropathy." (PMID 36313695, 2022). "LncRNA NEAT1 affected pyroptosis via targeting the miR-34c and NLRP3 in diabetic nephropathy." (PMID 36313695, 2022).
diabetic nephropathy (continued). "Moreover, NEAT1 has been shown to enhance ECM accumulation and plays a crucial role in diabetic nephropathy fibrogenesis." (PMID 34414852, 2021). "In conclusion, this research provides evidence that NEAT1 is involved in the protective effect of Klotho against renal tubulointerstitial fibrosis and EMT in renal tubular epithelial cells through the ERK1/2 signaling pathway in diabetic kidney disease." (PMID 32054986, 2020). "The Real-time PCR data showed that miR-222-3p expression in patients with diabetic nephropathy was significantly lower than that in controls, and a negative correlation between NEAT1 and miR-222-3p expression was observed in diabetic nephropathy patients." (PMID 33585566, 2020). "It was reported that the lncRNA NEAT1/miR-34c/NLRP3 axis regulates pyroptosis activation and that the lncRNA MEG3/miR-181a/Egr-1/TLR4 signaling pathway promotes fibrosis and the inflammatory response, both of which mediate the progression of diabetic nephropathy." (PMID 34941711, 2021).
endometrial cancer (22 papers, 2018 to 2025). Primary or metastatic malignant neoplasm involving the endometrium (mucous membrane that lines the endometrial cavity). "A recent study revealed that cancer-associated fibroblast cells (CAFs)-derived exosomal NEAT1 can target the growth, metastasis, and progression of endometrial cancer." (PMID 37310654, 2023). "NEAT1 expression was significantly increased in early-stage endometrial cancer tissue samples, and high NEAT1 expression was associated with poor prognosis." (PMID 37310654, 2023). "When used alone, progesterone causes G0/G1 cell cycle arrest in endometrial cancer cells through regulating NEAT1 and miRNA-146b-5p." (PMID 34683909, 2021). "Our study aims to investigate the roles of embryonic lethal abnormal vision-like 1 (ELAVL1) and long non-coding RNA (LncRNA) NEAT1 in endometrial cancer (EC), focusing on their underlying molecular mechanisms.We obtained EC cell lines (HEC-1A, Ishikawa, RL95–2, HEC-1B, and AN3CA) from ATCC." (PMID 40018990, 2025). "Moreover, exosomal NEAT1 derived from cancer-associated fibroblasts (CAFs) promotes the progression of endometrial cancer." (PMID 36011001, 2022). "In summary, our study showed that ELAVL1 regulated the malignant behavior of endometrial cancer cells through the modulation of LncRNA NEAT1-mediated regulation of Beclin1 expression." (PMID 40018990, 2025). "In our study, we discovered that ELAVL1 plays a significant role in regulating the malignant behavior of endometrial cancer cells through the modulation of LncRNA NEAT1-mediated regulation of Beclin1 expression." (PMID 40018990, 2025). "LncRNA is involved, among others, in initiating a prometastatic endometrial cancer phenotype; nuclear paraspeckle assembly transcript 1 (NEAT1)-mediated miR-361 sponging activates the STAT3 axis." (PMID 39188680, 2024). "In endometrial cancer tissues, NEAT1, HMGA1, and β-catenin were all considerably elevated, while miR-214-3p was dramatically downregulated." (PMID 37310654, 2023). "In endometrial cancer cells, the expression level of NEAT1 increased and positively interacted with lymphoid enhancing factor 1 (LEF1), c-myc, and MMP9 through the Wnt/β-catenin signaling." (PMID 37310654, 2023). "Here, we listed several NEAT1/miRNA/mRNA axes that are essential in breast, cervical, ovarian, and endometrial cancers." (PMID 37310654, 2023). "Another study demonstrated progesterone-mediated regulation of the Wnt/β-catenin signaling pathway via regulation of lncRNA NEAT1/miR-146b-5p contributing to endometrial cancer growth inhibition." (PMID 34068065, 2021). "According to Peixin Dong, NEAT1 facilitated the progression of aggressive endometrial cancer by repressing miR-361 expression and increasing STAT3 signalling." (PMID 33546665, 2021). "This phenomenon is exemplified in various cancers: WEE2-AS1 and SNHG3 in colorectal cancer; NEAT1 in endometrial cancer; LINC00355 in bladder cancer; SNHG3 in breast cancer; TUC338 in laryngeal squamous cell carcinoma; FTX in oral squamous cell carcinoma; and NNT-AS1 in pancreatic cancer." (PMID 39717771, 2024). "It has been reported that the expression of NEAT1 in endometrial cancer is elevated." (PMID 37310654, 2023). "High expression of NEAT1 was found in endometrial cancer tissues and cell lines." (PMID 37310654, 2023). "The inhibition of NEAT1 expression enhances the reactivity of endometrial cancer cells to TX." (PMID 34510316, 2022). "In this study, progesterone exerted suppressive influence on endometrial cancer progression via regulation of the lncRNA NEAT1/miR-146b-5p-mediated Wnt/β-catenin signaling pathway, potentially revealing new strategies for developing more effective therapeutics." (PMID 34068065, 2021). "Similarly, the long non-coding RNA NEAT1/miR-361/STAT3 axis drove aggressive endometrial cancer progression." (PMID 33896365, 2021). "Progesterone by regulating the NEAT1/miR-146b-5p axis via Wnt/β-catenin pathway could inhibit endometrial cancer cell cycle and viability." (PMID 33330110, 2020).
endometrial cancer (continued). "Therefore, NEAT1 may function as a potent biomarker for the prediction and treatment of breast, ovarian, cervical, and endometrial cancers." (PMID 37310654, 2023). "Within the context of endometrial cancer, CAF-derived NEAT1 operates as a “ceRNA” for miR-26a/b-5p, leading to the overexpression of target genes STAT3 and YKL-40, and thus modulating tumor behavior." (PMID 39717771, 2024). "The lncRNA nuclear paraspeckle assembly transcript 1 (NEAT1), an estrogen-inducible lncRNA, is reported to be upregulated in TX-resistant endometrial cancer." (PMID 34510316, 2022). "It was shown that incubation with 20 μM progesterone significantly decreased the expression level of the NEAT1, miR-146b-5p, LEF1, c-myc, and MMP9 genes of the WNT/β-catenin signaling pathway in Ishikawa endometrial cancer cells, wherein the cell cycle was inhibited in the G0/G1 phase." (PMID 34683909, 2021). "In endometrial carcinoma, a distinct regulatory pattern was observed, with LINC00582, LINC-ROR, MEG3, NEAT1, and SNHG12 displaying significant negative correlations." (PMID 41303609, 2025).
melanoma (21 papers, 2013 to 2025). A malignant, usually aggressive tumor composed of atypical, neoplastic melanocytes. "Other results suggest that the higher expression of NEAT1 occurs in melanoma patients showing a complete response to anti-PD-1/PD-L1 immunotherapy." (PMID 40282449, 2025). "NEAT1 is a well-described lncRNA in melanoma that exerts its oncogenic activity by regulating the expression of E2FR3, KLF3, and SMAD2 by directly binding miR-495-3p, miR-23a-3p, and miR-200-3p." (PMID 40282449, 2025). "GNA triggered ferroptosis in melanoma cells by decreasing lncRNA nuclear-enriched abundant transcript 1 (NEAT1) and downregulating levels of SLC7A11/glutathione peroxidase 4 (GPX4)." (PMID 40900835, 2025). "In another analysis by Toker and colleagues, the researchers observed significant upregulation of NEAT1 in the tissue of melanoma patients that responded to immunotherapy." (PMID 41463281, 2025). "The over-expressions of both NEAT1 and SNHG29 are all associated with poor survival in TCGA melanoma cohort." (PMID 36765063, 2023). "While lnc NEAT1 is known to be upregulated in melanoma, downregulation of lnc NEAT1 induces ferroptosis through weakening of the direct binding to SLC7A11, indirectly resulting in inhibiting GPX4 and inducing ferroptosis." (PMID 37795022, 2023). "For example, NEAT1 has been shown to promote the proliferation, migration and invasion of melanoma cells as well as A375 cells, by interfering the regulation of multiple microRNAs and their target genes." (PMID 36765063, 2023). "NEAT1 promotes the proliferation, migration, and invasion of melanoma cells by modulating miR-495-3p/E2F3 axis." (PMID 34247598, 2021). "From these results, it can be deduced that NEAT1 promoted melanoma progression through inhibiting miR-200b-3p." (PMID 33202380, 2020). "NEAT1 was also proved to facilitate the melanoma cell proliferation, migration, and invasion via regulating miR-495-3p and E2F3." (PMID 33392203, 2020). "From these results above, we can conclude that NEAT1 suppressed miR-200b-3p as a miRNA sponge in melanoma." (PMID 33202380, 2020). "The lncRNA NEAT1 has been reported to facilitate melanoma cell proliferation, migration, and invasion via regulating miR-495-3p and E2F3." (PMID 33392203, 2020). "RT-qPCR and RNAscope assays revealed that expression of NEAT1 in melanoma tissues (n=18) was significantly higher than that in benign naevus (n=18)." (PMID 33202380, 2020). "Few research has established the role of NEAT1 in melanoma progression, and some miRNAs are identified in the meantime, such as miR-23a-3p, miR-495-3p, and miR-224-5p." (PMID 33202380, 2020). "Taken together, the NEAT1/miR-200b-3p/SMAD2 signaling pathway promotes melanoma via activation of EMT, cell invasion and is related with immune responses, which provides new insights into the molecular mechanisms and therapeutic targets for melanoma." (PMID 33202380, 2020). "Next, we wanted to monitor the regulation of melanoma tumors through the targeting between NEAT1 and miR-23a-3p." (PMID 31462890, 2019). "Through regulation in the expression of KLF3 by miR-23a-3p, NEAT1/miR-23a mediated melanoma proliferation, migration, and invasion." (PMID 31462890, 2019). "In this study, we observed that the expression of NEAT1 was significantly upregulated in melanoma tissues, which remarkedly promoted the cells’ proliferation, cell migration, and invasion in melanoma cell lines." (PMID 31462890, 2019). "Through the induction of EMT, NEAT1 stimulates the invasion and migration of melanoma cells." (PMID 41463281, 2025). "According to the data presented above, NEAT1 may represent a novel clinical treatment target for melanoma." (PMID 37215082, 2023).